CD80 (CD80 molecule)
Diseases named in the same sentence as CD80 in open-access papers (continued):
Sharing a sentence is not in itself a finding about the gene and the disease.
tumor (continued). "Correlation analyses showed that associations between CD80 on APC subsets vs. CD69 on T cell subsets defined by CD103 and CD39 were generally negative in the tumor and colon." (PMID 34680397, 2021). "There was a positive correlation of CD80 and PD-L1 on APCs in tumor and colon, which suggests a negative feedback loop where CD80+ APCs that responded to activated T cells upregulate PD-L1 to reduce stimulatory cues from T cells." (PMID 34680397, 2021). "CD28 and CTLA-4 share a pair of ligands, CD80 and CD86, that are expressed on APCs or tumor cells." (PMID 34439774, 2021). "Notably, Ocs-P administration restored the expression of CD80, CD86, and MHC-I in lineage-CD11c+MHC-II+ splenic DCs induced by tumor injection." (PMID 33105813, 2020). "It is important to note that only the expression of CD80 reached significance when comparing tumor vs. no-tumor tissues in both ethnicities." (PMID 32983990, 2020). "Flow cytometry analysis of protein expression profile of unmodified TMVs showed that TMVs express tumor and immune cell markers such as cancer stem cell markers (CD24 and CD44), co-stimulation (CD80 (B7-1)), immunosuppression (CD47, PD-L1), and innate immune cells (Gr1)." (PMID 32295135, 2020). "Dysregulation of CD80 may be immunosuppressive in the TME and taken advantage of by tumor cells of CRC to escape immunity." (PMID 33419310, 2020). "One of the mechanisms is lacking of co-stimulatory molecules (such as CD80 and CD86), which is caused by the tumor provided inflammatory background and lead TILs become “exhausted”." (PMID 32579541, 2020). "In our settings, adding butyrate in mice treated with IgG2b did not induce modification of CD86/CD80 expression (in tumor-bearing mice)." (PMID 32358520, 2020). "It was also found that platinum-containing drug oxaliplatin induced immunogenic cell death (ICD) in LLC cells, activating dendritic cells with CD80+CD86+ phenotype and enhancing cytotoxic CD8+ T cells in LLC tumor tissues, which resulted in tumor regression in a mouse model of lung cancer." (PMID 33194645, 2020). "In particular, we identify CD80, 4-1BB, and OX40 as promising candidate pathways for co-targeting with a FAK inhibitor and show that these combinations can unlock anti-tumor immune responses capable of driving complete regression of at least some mouse tumor models." (PMID 31959281, 2020). "For example, in advanced tumors where tumor cells tend to evade anti-tumor responses by downregulating major histocompatibility complexes (MHC), minimizing CD80/86 on tumor cells may be redundant as APCs remain the only targets of Tregs." (PMID 33375291, 2020). "Under the costimulation of secreted IL-2 and exosomal CD80, the expression of exosomal peptide MHC I is passed to CD8+ T cells, thereby stimulating the proliferation of CD8+ T cells and inducing more effective anti-tumor immunity in vivo." (PMID 33183286, 2020). "To reinvigorate CTLA-4-targeted immunotherapy, we and others have reported that rather than blocking CTLA-4 interaction with its cognate targets, CD80 and CD86, anti-CTLA-4 antibodies achieve their therapeutic responses through selective depletion of regulatory T cells in the tumor microenvironment." (PMID 31991588, 2020). "However, CTLA-4 outcompetes CD28 for CD80/CD86 binding, thereby, inhibiting the downstream TCR signaling and hampering anti-tumor CD8+ T cell function." (PMID 33256089, 2020). "When assessing the TAM phenotype with M1 (CD80+) and M2-markers (CD206+), the distribution of both populations was markedly different with M1-like macrophages mostly populating the tumor border, whereas M2-like macrophages were mostly present in the tumor core." (PMID 32042342, 2020). "In addition, CD28 and CTLA4 expression has been reported in activated mouse NK cells, the interaction between CTLA4 and CD80 has a direct effect on IFN-γ release by NK cells, and CTLA4 expression has been reported in mouse tumor infiltrating NK cells." (PMID 31898484, 2020).
tumor (continued). "Neither CD80 nor CD86 are expressed on non-haematological tumour cells, so the main effects of CTLA-4 are thought to occur within the secondary lymphoid organs." (PMID 32937961, 2020). "In addition to roles in naïve T cell priming, CD80 and CD86 induce proliferation and IFN-γ expression in exhausted, tumor-specific CD8+ T cells within the TME following vaccination with moDCs." (PMID 31947933, 2020). "Importantly, HDACi have also been shown to increase the expression of costimulatory molecules on the surface of tumor cells, such as CD40, CD80, and 4–1BB." (PMID 32500025, 2020). "M1 macrophage-related genes include IL-6, IL-8, CD80, PIM1, RTP4, and SLC11A1, and studies have shown that after metformin treatment, the expression of M1-related factors in tumor cells can be enhanced or weakened, thus affecting the prognosis of the tumor." (PMID 33193731, 2020). "Oncolysis induced by a recombinant poliovirus-rhinovirus chimera exposed the tumor antigens, while DCs co-cultured with the supernatant from the chimera-infected tumor cells exhibited increased expression of type I IFNs, CD40, CD80, and CD83, suggesting that this virus promotes APC maturation." (PMID 33680911, 2020). "In absence of TLR stimulation, circulating and tumor‐infiltrating 20 h‐cultured cDC2s and pDCs displayed higher levels of CD80, CD40 and/or CD86 (% and/or MFI) when compared to HD." (PMID 33282290, 2020). "For further validation, BmDCs Figure S5BA; optimum upregulation in 32 h; Figure S5BB) were exposed to tumor-conditioning media (TCM) to mimic tumor milieu, and upregulated MHC-I, CD80, and CCR7 expression was observed (Figures 5B1,B2) following NLGP supplementation (CD11c+ cells 77.77–89.93%)." (PMID 32211313, 2020). "Costimulatory molecules (CD80), intercellular adhesion molecule 1 (ICAM-1), stress ligands (NKG2DL), and death receptor Fas on the tumor surface are also upregulated after radiation, which makes the tumor cells more sensitive to the recognition and killing of cytotoxic T lymphocyte." (PMID 32992835, 2020). "Therefore, distinguishing CD80 and CD86 expression between tumor cells and APCs is required for a more accurate prognosis prediction in EC patients." (PMID 31771653, 2019). "CD80+PD-L1+ mouse tumor cells similarly did not bind PD-1-Fc, while CD80−PD-L1+ mouse tumor cells bound PD-1-Fc." (PMID 31001479, 2019). "Two signals are needed to induce T cell activation: binding of the MHC receptor with the tumour antigen to the TCR and binding of CD80/CD86 (also known as B7-1 or B7-2), which is primarily expressed on antigen presenting cells (APCs), to CD28 expressed by T cells." (PMID 31561518, 2019). "Interestingly, Trapoxin A treatment led to the up-regulation of costimulatory and adhesion molecules (CD80, CD86, HLA-DR, HLA-ABC, and ICAM-1) in AML cells, inducing tumor immunity." (PMID 31739588, 2019). "The expression of CD80 and CD86 on tumor cells or TIICs (especially APCs) may have a bias to suppress or activate the antitumor immune response, respectively." (PMID 31771653, 2019). "Our finding that human CEC from preneoplastic lesions overexpress CD80 and HLA ABC molecules compared to normal and tumor-derived CEC fosters the hypothesis that dysplastic cells can be recognized and eliminated in human sporadic CRC." (PMID 31072360, 2019). "Moreover, in a tumor progression situation the miR-424 can directly block the binding of PD1/PDL1 and CD80/CTLA-4 action and thereby induce tumor suppression." (PMID 31337863, 2019). "We found that MC38 and LLC tumor cells do not express CD80 and CD86 costimulatory molecules and this phenotype is not modified by CIITA expression." (PMID 31417570, 2019). "With increase in tumor size, the MHC-IIhi TAMs in the TME of 3BD9 vaccinated tumors seemed to gradually lose Ly6G expression, produce minimal T cell stimulatory surface antigens (CD80), and elevated levels of PD-L1, in contrast to PBS vaccinated tumors." (PMID 31882679, 2019).
tumor (continued). "Notably, CD80 and CD86, which are expressed on both tumor cells and TILs, can interact with CD28 on T cells to activate costimulatory signaling and with CTLA-4 on activated T cells to initiate inhibitory signaling." (PMID 31771653, 2019). "Additionally, the number of CD80- and mannose receptor C type 1 (MRC1)-expressing cells was decreased upon LPS administration in the tumor of the xenograft tumor." (PMID 29690614, 2018). "However, the CD80+ TAMs recruited and polarized by CP1 represent an M1 macrophage proven to inhibit tumor growth and promote cytotoxic T cell activity." (PMID 29686284, 2018). "Treatment of CTLA-4 expressing tumor cell lines with recombinant forms of the CTLA-4 ligands CD80 and CD86 induced caspase-8-dependent apoptosis and the level of apoptotic tumor cells was reduced by soluble CTLA-4 and anti-CTLA-4 single-chain variable fragment antibodies." (PMID 29682176, 2018). "In the spleens of CT26 tumor-bearing mice, CD80- and MRC1-expressing cells were present but they did not increase following exposure to LPS." (PMID 29690614, 2018). "In fact, the dysregulated expression of both CD80 and CD86 could negatively affect CTL and Treg functions allowing tumor spread." (PMID 30123257, 2018). "Moreover, regardless of costimulation from the tumor cell, anti-CD19 AbTCR-T cells had similar anti-tumor activity compared to CAR-T cells in both Raji and CD80-/CD86- tumor models." (PMID 30479831, 2018). "Taken together, these results suggest that the physiological function of CD80-expressing cells after LPS signaling is retained in the xenograft tumor model but not the allograft tumor model." (PMID 29690614, 2018). "The elderly tumor microenvironment reduces MHC-I/II and CD80 on DCs and IFN-γ in T cells." (PMID 30560130, 2018). "The tumor-inducing effect of CD274 may also involve other immunoregulatory molecules, such as CD80, whose intragraft gene expression level correlated positively with CD274 in transplant recipients as reported here." (PMID 29642405, 2018). "However, elderly tumor-bearing mice demonstrated reduced MHC-I, MHC-II and CD80 on CD11c+ cells, and decreased IFN-γ by CD8+ and CD4+ T cells within tumors, compared to young counterparts, implying loss of function." (PMID 30560130, 2018). "siRNAs blocking the PD-1/PD-L1 or CTLA-4/CD80, /CD86 pathways could reduce the metastasis of tumor cells." (PMID 30564277, 2018). "In contrast, CT26/HER2 cells induced a higher level of IFN-γ production in an antigen-non-specific manner, attracted higher levels of MDSCs in their tumor tissue and expressed CD80 onto their surface, which was not the case for 4T1.2/HER2 cells." (PMID 28460461, 2017). "The TC-1 and MC32 cells displayed no CD80, CD86 or CD40 surface expression, supporting the notion that CD80 is not directly associated with IFN-γ production and tumor progression." (PMID 28460461, 2017). "For example, tumor cells are believed to promote the expression of CTLA-4, which is a molecule expressed by T cells that competes with CD28 for the co-stimulatory molecule CD80 (B7.1), thereby suppressing T cell activation." (PMID 27092248, 2016). "The Carthamus tinctorius L., one of AVS073′s components, was reported to promote the expression of maturation markers (CD80, MHC class I and II) in mouse bone-marrow-derived DCs and maintained the high profile of maturation markers (CD80, CD86, MHC class I and II) in tumor antigen pulsed-DCs." (PMID 27899095, 2016). "The other protein type includes proteins that exist in specific types of exosomes; for example, MHC and costimulatory CD80 or CD86 molecules are abundant in exosomes surface originating from DCs and B lymphocytes, and a number of tumor antigens are contained in tumor cell-derived exosomes." (PMID 27686593, 2016). "Furthermore, the expressions of CD80 and CD86 in Treatment group were significantly higher than Tumor group especially on the back of a few time points the same as the results of CD11c." (PMID 27669687, 2016).
tumor (continued). "Next, we asked whether CD80 expression on phagocytes was a prerequisite for CTL activation and tumor spheroid size reduction." (PMID 25871398, 2015). "Phagocyte activation not only promotes tumor-associated antigen presentation and upregulates costimulatory B7 family molecules such as CD80/CD86 to trigger anti-tumor lymphocyte activation, but also initiates counter-regulatory signals that attenuate activation." (PMID 25871398, 2015). "This dichotomy of CD80 expression was found to be critical in the anti-tumor response to systemic IL-12 and peritumoral IL-2 immunotherapy, as tumor generated from cell lines lacking CD80 expression failed to respond." (PMID 26690220, 2015). "One may envisage that such a decrease in intracellular CTLA-4 levels would decrease the T-cell activation threshold during contact with dendritic cells that express CD80 and CD86 and enhance their proliferation and anti-tumor abilities." (PMID 26110267, 2015). "In this setting, mPGES-1−/− monocyte-derived tumor spheroid-infiltrating macrophages indeed expressed higher CD80, but not CD86, levels compared to wildtype macrophages." (PMID 25871398, 2015). "These Tregs might tolerize tumor infiltrating antigen presenting cells through IL-10 induced immunoglobulin-like transcripts (ILT)-2, ILT3, ILT4, and decreased expression of CD40, CD80, and CD86 costimulatory molecules." (PMID 25972872, 2015). "Not surprisingly, galectin-9, MHC class II and CD80 is present on a variety of cells in the tumor microenvironment including B cells, macrophages, DCs and monocytes." (PMID 25614821, 2015). "Indeed, by inhibiting CTLA-4 in 19z1-CD80+ T cells in which the CD28 signal comes from endogenous CD28 receptors activated by CD80 ligation, we almost reached the anti-tumor capacity of 19-28z+ T cells, in which CD28 costimulation is provided trough the CAR." (PMID 26110267, 2015). "Due to the increased CTLA-4 expression observed on TILs after selection of α-PD-L1 resistant tumors, and increased CD80/86 expression on remaining tumor cells, we hypothesized that blockade of both CTLA-4 and PD-L1 might lead to better tumor control." (PMID 25992292, 2015). "In addition, they observed that tumor CD20+ B cells expressed several markers of antigen presentation, such as MHC Class I and II molecules, as well as the costimulatory molecules CD80 and CD86." (PMID 25755654, 2015). "Interestingly, three markers were differentially expressed in naïve and tumor-induced monocytes including CD71, CD115, and CD80, indicating a distinct MDSC phenotype in tumor-bearing mice compared to naïve mice." (PMID 25538893, 2014). "DCs from the non-adherent cell fraction in the DC/tumor electro-fusion products had significant up-regulation of MHC class II as well as CD80, CD86 and CD83." (PMID 24466232, 2014). "Interestingly, we found that the T cell costimulatory molecules CD80 and CD86 and the mature molecule CD83 were substantially upregulated on the tumor-activated γδ T cells, along with the obvious increased expression of HLA-DR (n = 9)." (PMID 24741609, 2014). "In addition, tumor expression of CD80 also enhances CTL effector functions and facilitates better tumor destruction." (PMID 23671644, 2013). "In addition, CD80 and CD86 surface expression was used to gauge the activation profile of CD11c+ DC found within the tumours." (PMID 24251770, 2013). "On the contrary, tumors that are induced to express costimulatory molecules that activate T cells, such as B7.1 (also known as CD80), and B7.2 (also known as CD86) are cleared by the immune system and thus may be used as a strategy to promote tumor immunity." (PMID 23533456, 2013). "Other factors which may influence the rate of cell killing are firstly susceptibility of individual tumor cell lines to lysis and secondly the presence of cofactors such as CD80 and CD86 on the tumor cells which may augment killing." (PMID 23263452, 2013).
tumor (continued). "Third, DAC-induced CD80+ tumor cells, but not CD80− tumor cells induced potent anti-tumor CTL responses." (PMID 23671644, 2013). "All mice that received CD80− EL4 cells grew tumors, while majority (60–80%) of mice that received DAC-treated CD80+ EL4 cells failed to grow tumor." (PMID 23671644, 2013). "Based on the fact that CTLA4Ig binds with high affinity to CD80/CD86, we hypothesized that CD80 or CD86 might play in role in the ability of CTLA4Ig to enhance NK cell functions against tumor metastasis." (PMID 24349559, 2013). "Furthermore, TLR9 agonist activated NKDCs by upregualting the expression of both CD80 and CD86, while RT increased the tumor infiltration of NKDCs." (PMID 22666458, 2012). "Moreover, preventing CD80 expression on MDSC or the use of anti-CTLA-4 antibodies delay tumor growth, suggesting that CTLA-4/CD80 interaction between MDSC and Treg is necessary for their activity or their development." (PMID 22822406, 2012). "Mouse bone-marrow-derived DCs first activated with the TLR4 ligand LPS and exposed to tumor-induced Treg maintain expression of CD80, CD86, and CD40, produce IL-12 or TNF-a, and are not impaired in their allostimulatory activity." (PMID 22110524, 2011). "Subcutaneous injections of CpG at the contra lateral side do increase the number of DC in the local lymph node (data not shown), but not in the tumor-draining lymph node and fail to enhance antigen uptake and CD80 expression." (PMID 20020049, 2009). "When pooled serum (n = 5 for each group) from naïve mice, tumor-bearing mice, mice treated with PC61 alone, or mice treated with two weekly injections of the vaccine cell-line AGN2a-CD80/CD86 alone was used to screen the cDNA library 0, 0, 0, or 5 unique clones, respectively, were identified." (PMID 17397536, 2007). "Removal of the tumour also induced a decrease, although not significant, of the percentage of CD80+DCs (pre: 10.52 ± 3.53%; post: 6.41 ± 1.70%; P=n.s)." (PMID 14562018, 2003). "KCNN4 has been shown to have positive correlations with several costimulatory molecules (CD276, CD40, CD70, CD80, CD86), immune signaling receptors (IL2RA, MICB, NT5E), and multiple TNFRSF family members, suggesting its involvement in immune modulation, inflammation, and tumor‐immune interactions." (PMID 40952239, 2025). "Therefore, targeting those epitranscriptomics mechanisms that govern the CD80-CTLA-4 competition could optimize immunotherapy strategies and reinforce anti-tumor responses." (PMID 40565233, 2025). "Notably, anti-CD80/CD86 as a single agent or in combination with radiation also resulted in an overall decrease in CD4 T cells as a percent of live cells in the tumor, without impacting CD8 T cell proportions." (PMID 41417245, 2025). "Concomitant quantification of PD-L1-CD80 cis-heterodimers on tumor cells stratifies patients further: where this inhibitory pair is abundant, adding a PD-L1 antagonist liberates both CD80 for CD28 co-stimulation and PD-L1 from PD-1 restraint, amplifying anti-tumor immunity." (PMID 41112277, 2025). "Thus, a relative increase in CD86 may be related to an anti-TME: the distinct ratios of CD80 and CD86 in CCH and HS suggest an involvement of these molecules in the behavior of the investigated neoplasia." (PMID 40271486, 2025). "They demonstrated that in settings where only the trans-PD-L1/CD80 interaction can exist (implantation of CD274KO tumor cells in CD80KO mice), blocking this interaction, without interfering with the PD-1/PD-L1 interaction, is sufficient to increase anti-tumor immunity." (PMID 41425548, 2025). "CD80’s role in the regulation of tumor immunity via RNA modifications has not been clarified yet." (PMID 40565233, 2025). "Finally, analysis of CNV patterns in key co‐stimulatory and co‐inhibitory genes (e.g., CD80, CD86, PD‐L1) revealed a distinct inverse relationship between Q1 and Q4 groups: Q1 tumours exhibited higher frequencies of gene amplifications, whereas Q4 tumours demonstrated more frequent deletions." (PMID 40596639, 2025).